HNF4A (hepatocyte nuclear factor 4 alpha)
Description:
Transcriptional regulator which controls the expression of hepatic genes during the transition of endodermal cells to hepatic progenitor cells, facilitating the recruitment of RNA pol II to the promoters of target genes. Activates the transcription of CYP2C38 (By similarity). Represses the CLOCK-BMAL1 transcriptional activity and is essential for circadian rhythm maintenance and period regulation in the liver and colon cells.
Synonyms: TCF-14; HNF4; NR2A1; TCF14; FRTS4; HNF4a7; HNF4a8; HNF4a9; HNF4alpha; MODY; MODY1; NR2A21; TCF
Tractability: Small molecule: an approved drug acts on it; a structure with a bound ligand is known; a high-quality ligand is known; it has a binding pocket of medium quality; it belongs to a druggable protein family. PROTAC: UniProt records ubiquitination sites on it; ubiquitination databases record sites on it; a small molecule that binds it is known.
Safety:
Unwanted effects reported when the protein is acted on. In parentheses: how it was acted on, where the effect was seen, and who reports it.
anemia (source: ClinPGx)
Gene: Protein-coding gene on chromosome 20 (44,355,699 to 44,432,845, forward strand). Ensembl gene ENSG00000101076.
Subcellular location: Nucleus
Subcellular location (Human Protein Atlas): Nucleoplasm
Pathways (Reactome):
Developmental Biology: Nephron development; Regulation of gene expression in beta cells
Gene expression (Transcription): Nuclear Receptor transcription pathway
Gene Ontology:
Molecular function: DNA binding; DNA-binding transcription factor activity; fatty acid binding; nuclear receptor activity; protein binding; protein homodimerization activity; sequence-specific double-stranded DNA binding; signaling receptor binding; transcription cis-regulatory region binding; DNA-binding transcription activator activity, RNA polymerase II-specific; DNA-binding transcription factor activity, RNA polymerase II-specific; RNA polymerase II cis-regulatory region sequence-specific DNA binding; RNA polymerase II-specific DNA-binding transcription factor binding; chromatin binding; sequence-specific DNA binding; zinc ion binding
Biological process: blood coagulation; lipid homeostasis; negative regulation of cell growth; negative regulation of cell population proliferation; negative regulation of DNA-templated transcription; positive regulation of DNA-templated transcription; positive regulation of ornithine catabolic process; positive regulation of transcription by RNA polymerase II; regulation of circadian rhythm; regulation of lipid metabolic process; regulation of transcription by RNA polymerase II; xenobiotic metabolic process; cell differentiation; cholesterol homeostasis; glucose homeostasis; phospholipid homeostasis; regulation of insulin secretion; response to glucose; triglyceride homeostasis; intracellular receptor signaling pathway; regulation of DNA-templated transcription
Cellular component: cytoplasm; nucleoplasm; nucleus; chromatin
Genetic constraint (gnomAD): Loss-of-function variants: 15 observed, 52.57 expected, observed/expected ratio (o/e) 0.29, 90% interval 0.19 to 0.44. The upper end of that interval is the gene's LOEUF score, 0.44, which puts it in group 1 of 6, group 1 being the genes least tolerant of losing a copy. Missense variants: 479 observed, 671.7 expected, observed/expected ratio (o/e) 0.71, 90% interval 0.66 to 0.77. Synonymous variants: 280 observed, 275.25 expected, observed/expected ratio (o/e) 1.02, 90% interval 0.92 to 1.12.
Gene-disease validity (ClinGen):
ClinGen rates the evidence that HNF4A causes each of these diseases.
monogenic diabetes (autosomal dominant): Definitive. Diabetes mellitus that is caused by mutations in a single gene.
Homologues: Orthologues: chimpanzee HNF4A (97% identical), macaque HNF4A (97% identical), dog HNF4A (96% identical), pig HNF4A (95% identical), guinea pig HNF4A (95% identical), rat Hnf4a (94% identical), mouse Hnf4a (93% identical), rabbit HNF4A (89% identical), tropical clawed frog hnf4a (80% identical), zebrafish hnf4a (79% identical), Caenorhabditis elegans nhr-69 (31% identical), Drosophila melanogaster usp (26% identical), and 25 more. Paralogues in human: HNF4G (68% identical), RXRA (34% identical), RXRB (32% identical), RXRG (32% identical), NR2F1 (31% identical), NR2F6 (31% identical), NR2F2 (30% identical), NR2E3 (27% identical), NR2C2 (27% identical), NR2E1 (26% identical), NR2C1 (24% identical).
Diseases named in the same sentence as HNF4A in open-access papers:
HNF4A is named in the same sentence as 275 diseases in open-access papers, as found by Europe PMC text mining. Sharing a sentence is not in itself a finding about the gene and the disease. The quoted sentences say what the papers report.
diabetes (213 papers, 2003 to 2026). "We identify a novel rare variant in HNF4A - a canonical monogenic diabetes / MODY gene, in which missense variants would be expected to increase T2D risk." (PMID 42238389, 2026). "This case emphasizes that spontaneous HNF4A-MODY is highly susceptible to misdiagnosis as either type 1 or type 2 diabetes mellitus." (PMID 40589512, 2025). "Thirdly, we only incorporated 20 patients with monogenic diabetes, which is difficult to highlight the effect of mutations in HNF1β, HNF4A, and HNF1A genes associated with Lp(a) expression on Lp(a) concentration in patients with early-onset T2DM." (PMID 40370778, 2025). "The pathophysiological mechanisms of HNF4A-related diabetes resemble those of mutations in the Hnf1α gene." (PMID 40149950, 2025). "In humans, HNF4α mutations are responsible for Diabetes mellitus subtype MODY1, which has an age-determining onset." (PMID 41017587, 2025). "HNF4A–maturity-onset diabetes of the young (MODY1) is a relatively rare subtype of monogenic diabetes caused by loss of function of the HNF4A gene, which encodes the transcription factor HNF4α." (PMID 38745825, 2024). "In conclusion, we recommend the use of the G6PC-linked reporter system in HepG2 cells to best capture the gradient of functional effect of HNF4A diabetes-associated variants." (PMID 38433330, 2024). "Hazard rate (HR) for age of onset of diabetes was significantly lower when comparing carriers of the c.-192C>G P2-HNF4A promoter variant with carriers of known disease-causing coding HNF4A variants (P < 0.001)." (PMID 38855865, 2024). "These insights provide a deeper understanding of the molecular mechanisms underlying β cell dysfunction in obesity and diabetes, emphasizing HNF4α as a potential therapeutic target for improving β cell resilience and function in metabolic diseases." (PMID 39741884, 2024). "Genetic sequencing detected a novel heterozygous missense HNF4A variant (c.742G > T, p.Asp248Tyr; referred as “D248Y”) in the patient and her relatives who presented with diabetes." (PMID 38745825, 2024). "Three ABCC8 variants (p.G1478R, p.L580_S581insFASL, and p.S986⁣∗) and two HNF4A variants (p.R63W and p.V382I) were previously reported to be associated with diabetes." (PMID 40302972, 2024). "As HNF4α is a transcriptional regulator of the insulin gene, these findings suggest a causal relationship between D248Y and the presentation of diabetes in this family." (PMID 38745825, 2024). "At the same time, HNF4A polymorphisms are associated with defective insulin secretion, leading to an increased risk of type 2 diabetes mellitus and metabolic syndrome." (PMID 37895816, 2023). "A large number of human genetic variations to HNF4α occur that alter the protein structure and function of HNF4α and are linked with diabetes, metabolic disorders, and some types of cancers." (PMID 37732120, 2023). "HNF4α is associated with several human diseases including diabetes, hemophilia, hepatitis, atherosclerosis, and inflammatory bowel diseases." (PMID 37239961, 2023). "Various genetic mutations and alterations in HNF4α are associated with diabetes, metabolic disorders, and cancers." (PMID 37732120, 2023). "One such gene is the nuclear receptor (NR) Hepatocyte Nuclear Factor 4 alpha (HNF4α), a liver-enriched transcription factor (TF) best known as a master regulator of liver-specific gene expression and mutated in Maturity Onset Diabetes of the Young 1 (MODY1)." (PMID 38111711, 2023). "A network-based meta-analysis identified HNF4A, a TF associated with gluconeogenesis and diabetes, as a central longitudinally dynamic biomarker for Parkinson’s disease." (PMID 37226244, 2023). "Recent research indicates that mutations in the HNF4A gene are involved in progressive β-cell dysfunction and hyperinsulinism, which can result in the establishment of early diabetes." (PMID 36037214, 2022). "Hepatic HNF4α expression is markedly decreased in diabetes and NAFLD which are commonly associated with hyperlipidemia." (PMID 35614477, 2022).
diabetes (continued). "Pathogenic variants in HNF1A and HNF4A cause progressive beta-cell dysfunction leading to diabetes whereas pathogenic variants in GCK cause stable mild hyperglycemia." (PMID 36257325, 2022). "Pathogenic variants in HNF1A and HNF4A show the highest risk of diabetes in clinically selected individuals but had substantially lower risk in clinically unselected settings." (PMID 36257325, 2022). "Similar to HNF1A, for individuals with a HNF4A pathogenic variants, the age-related penetrance of diabetes was lower in the family members, the Geisinger cohort and the UK Biobank compared to MODY probands (log rank test, all p < 8 × 10−11)." (PMID 36257325, 2022). "HNF4A has been associated with diabetes and has more recently been associated with reduction of proliferation in kidney cells, specifically renal cell carcinoma." (PMID 33778495, 2021). "They identified 12 differentially methylated CpG sites in the GDM-exposed group, two of which have been linked to monogenic diabetes (hepatocyte nuclear factor 4 alpha, HNF4A) and obesity (Ras responsive element binding protein 1, RREB1)." (PMID 34968300, 2021). "Firstly, the expression of EPHX1 is regulated by various transcriptional factors including GATA4 and HNF4A, two genes implicated in other forms of monogenic diabetes." (PMID 34342583, 2021). "In contrast, MODY1 patients carrying heterozygous mutations in HNF4A present diabetes due to impaired β cell function." (PMID 34295307, 2021). "Conversely, babies who inherit a pathogenic or likely pathogenic hepatocyte nuclear factor 4a (HNF4A) monogenic diabetes variant from their mother are at increased risk of high birth weight." (PMID 32533152, 2020). "HNF4A variants were reported to cause a bi-phasic phenotype in individuals presenting with macrosomia and transient HH during the neonatal period and diabetes in later life." (PMID 32185602, 2020). "Conversely, babies who inherit a pathogenic hepatocyte nuclear factor 4a (HNF4A) diabetes variant are at increased risk of high birth weight." (PMID 32533152, 2020). "Diabetes caused by mutations in the HNF4A gene is considerably less common than HNF1A (5% to 10% of the cases), but should be considered whenever clinical characteristics of HNF1A are present and genetic analysis does not detect a mutation in this gene." (PMID 32528556, 2020). "In keeping with previous studies, class 4–5 variants of GCK, HNF1A, and HNF4A accounted for the large majority (87%) of monogenic diabetes diagnoses." (PMID 31291970, 2019). "HNF4A mutations can cause hyperinsulinemic hypoglycemia and macrosomia in the neonatal period, as well as diabetes in adolescence or early adulthood caused by an impaired insulin secretory response to glucose in pancreatic β-cells." (PMID 30005691, 2018). "The HNF4A transcription factor is associated with gluconeogenesis and diabetes and has been identified as a central regulatory hub gene upregulated in the peripheral blood of PD patients." (PMID 29850016, 2018). "We first inquired if the HNF4A mutation or diabetes status prevented the differentiation of insulin+ cells in vitro." (PMID 28684784, 2017). "We then investigated if the HNF4A mutation or diabetes status impeded the initial in vitro maturation steps of the differentiated insulin+ cells." (PMID 28684784, 2017).
diabetes (continued). "Mutations in human HNF4A are associated with a type of inherited diabetes known as maturity-onset diabetes of the young, type 1 (MODY1)." (PMID 26935102, 2016). "Several HNF4A gene variants have been associated with the risk of developing type 2 diabetes mellitus." (PMID 25671620, 2015). "For instance, mutations in HNF4A are associated with increase in birth weight, macrosomia, hypoglycemia at birth and adolescent onset of diabetes." (PMID 26300908, 2015). "PPARγ is associated with obesity while decreased HNF4α is associated with fatty liver in mice and diabetes in humans." (PMID 26200659, 2015). "Annual screening of HNF4A-mutation carriers with oral glucose tolerance testing was recommended to diagnose diabetes mellitus at an early stage." (PMID 24299156, 2014). "More HNF4A-positive subjects with pre-diabetes and diabetes need to be studied to understand the impact of the HNF4A mutation on incretin effect." (PMID 24299156, 2014). "Regular screening of HNF4A mutation carriers using the oral glucose tolerance test has been recommended to diagnose diabetes mellitus at an early stage." (PMID 24299156, 2014). "MODY patients are mainly characterized by a severe impairment of insulin secretion, and MODY gene products, including HNF4α, are monogenic causes of an insulin secretion defect resulting in diabetes." (PMID 22952853, 2012). "As such, mutations in HNF4α cause a dominantly inherited form of diabetes known as Maturity Onset Diabetes of the Young 1 (MODY1), further underscoring its pivotal role in human pancreatic ß-cell function and metabolic regulation." (PMID 22952853, 2012). "The human HNF4A gene encoding HNF4α is mutated in a subtype of MODY (Maturity Onset Diabetes of the Young) and HNF4α is a central regulator of hepatic and pancreatic gene transcription." (PMID 22359515, 2012). "There is substantial evidence that HNF-4 has a unique role in glucose-dependent insulin secretory pathways, since mutations within the HNF-4α gene are linked to the monogenetic disorder Mature Onset Diabetes of the Young (MODY-1)." (PMID 21731631, 2011). "Mutations in HNF1A and HNF4A (encoding for hepatocyte nuclear factor 1α and 4α) are responsible for the most common form of monogenic diabetes." (PMID 20523905, 2010). "The transcription factors Hnf1α and Hnf4α control pancreatic islet β-cell function and growth, and mutations in their genes cause closely related forms of diabetes." (PMID 20523905, 2010). "Previous studies showed that homozygous Hnf1a mutant mice exhibit full blown diabetes, in contrast to β-cell and pancreas-specific Hnf4a mutations which only result in glucose intolerance." (PMID 20523905, 2010). "The orphan receptor hepatocyte nuclear factor 4 α (HNF4α) is a key regulator of many metabolic pathways and linked to several diseases including diabetes, atherosclerosis, hemophilia and cancer." (PMID 19440305, 2009). "In humans, mutations in the coding and promoter regions of HNF4α lead to Maturity Onset Diabetes of the Young 1 (MODY1), a heritable form of type 2 diabetes." (PMID 19440305, 2009). "We also associated HNF4A with diabetes consistent with its mutation in one form of diabetes." (PMID 41256165, 2025). "The early-onset T2DM cohort included patients with monogenic diabetes resulting from mutations in the HNF1β, HNF4A, and HNF1A genes associated with Lp(a) expression, which may help explain the lower levels of Lp(a)." (PMID 40370778, 2025). "Mutations in HNF1A, HNF4A, and HNF1β genes involved in Lp(a) expression account for more than 50% of monogenic diabetes with a known genetic cause, which may lead to the complexity of concentrations of Lp(a) in patients with T2DM." (PMID 40370778, 2025). "We further evaluated the molecular impact of the lead causal HNF4A T2D risk coding variant rs1800961 in human beta cells, in an attempt to uncover additional factors that may contribute to diabetes predisposition." (PMID 38909044, 2024).